S1PR2 (sphingosine-1-phosphate receptor 2)
Diseases named in the same sentence as S1PR2 in open-access papers (continued):
Sharing a sentence is not in itself a finding about the gene and the disease.
tumor (56 papers, 2013 to 2026). "In the recent years, studies turned their focus mainly on S1PR2 expressed on tumor cells and cancer-associated stem cells revealing both pro- and anti-tumor functions." (PMID 35163211, 2022). "Interrupting a direct impact of S1P on endothelial cells appears unlikely, since S1P was recently shown to stabilize tumor-associated blood vessels via endothelial S1PR1 (as well as S1PR2/3) signaling." (PMID 35163211, 2022). "Altogether, these data point to an enhanced cancer susceptibility, coupled to a faster/higher tumor growth rate in the S1PR2−/− background under inflammatory conditions." (PMID 33225975, 2020). "S1PR2 deficiency in Apcmin/+ at 21 weeks old led to a significant increase of total tumor load over the entire gastrointestinal tract compared with their littermates S1PR2+/+Apcmin/+ mice (p < 0.05), which was well evident in the distal colon (p = 0.033)." (PMID 33225975, 2020). "Consequently, little is known about the role of S1PR2 in tumor-associated inflammation." (PMID 35163211, 2022). "By crossing mice carrying a mutation in Apc and S1PR2 deficient mice, we observed acceleration of tumor formation, corroborating the hypothesis that the cross-talk of S1PR2 with intracellular Wnt/β-catenin signals can critically regulate proliferative responses and tumor development." (PMID 33225975, 2020). "On the contrary, the inhibition of S1PR2 by JTE-013 or the knockdown of S1pr2 by S1pr2-shRNA resulted in reduced tumor cell migration and invasion compared to control PSCs." (PMID 39519028, 2024). "According to the comparative results of tumourigenic growth between the Vector and oeS1PR2 groups, the subcutaneous tumour volume, mass, and S1PR2 expression of tumours were substantially higher in the oeS1PR2 group as compared to the Vector group." (PMID 36631680, 2023). "The experiments conducted in the In vivo conditions revealed that the overexpression of S1PR2 accelerated the growth of subcutaneous tumours." (PMID 36631680, 2023). "The growth curves suggested that the rate of tumour growth was notably slower in the sh-S1PR2 group." (PMID 36631680, 2023). "Cells transfected with sh-S1PR2 produced significantly smaller tumours as compared to cells transfected using sh-NC." (PMID 36631680, 2023). "Quantification of tumour weight and volume indicated that tumours in the sh-NC group were considerably larger in comparison to the ones in the sh-S1PR2 group." (PMID 36631680, 2023). "Silencing of S1PR2 decreased ki67 expression in tumours, whereas increasing S1PR2 expression had a contrasting effect." (PMID 36631680, 2023). "In vascular endothelial cells and bone marrow-derived cells, S1PR2 has an inhibitory effect on tumor angiogenesis and growth." (PMID 35862404, 2022). "S1PR1 is critical in the regulation of inflammatory processes driving neovascularisation, providing tumours with the nutrients and oxygen needed for cancer cell survival, with S1PR2 and S1PR3 having some compensatory functions in the absence of S1PR1." (PMID 35158806, 2022). "In summary, further studies are needed to analyze the impact of S1PR2 in immune cell functions in different tumor entities in order to decipher a possible role in turning cold into hot tumors." (PMID 35163211, 2022). "In contrast, S1PR2−/− tumor-bearing mice displayed an increased cell proliferation in tumor lesions compared to tumor-bearing S1PR2+/+ ones." (PMID 33225975, 2020). "S1PR2 overexpression attenuated tumor growth with statistical significance (p < 0.05) compared to the scramble." (PMID 33225975, 2020). "To gain insight into the mechanisms by which the loss of S1PR2 promotes tumorigenesis, we explored the role of S1PR2 as a brake of tumor proliferation and a potential tumor suppressor gene in vivo." (PMID 33225975, 2020). "Overall, these findings supported the key role of S1PR2 in arresting tumor growth and excluded its potential function in controlling the migratory capacity of epithelial tumor cells." (PMID 33225975, 2020).
tumor (continued). "In human CRC, the expression of S1P2 is drastically reduced, thus unveiling S1PR2 as a new candidate tumor suppressor gene in colorectal tumorigenesis." (PMID 33225975, 2020). "The effect of S1PR2 overexpression on the in vivo tumor cell growth was measured over 23 days after subcutaneous injection of RKO cells in female CD-1 nude mice." (PMID 33225975, 2020). "Several studies supported the anti-tumor function of the S1PR2 acting as a negative regulator of the proliferation and migration of cancer cells." (PMID 33225975, 2020). "This led to the further finding that SphK2/S1PR4 prevented nuclear translocation of S1PR2, which in turn, prevented tumor growth, providing support for sub-cellular distribution of S1PR2, which is important for oncogenic suppression." (PMID 28415564, 2017). "Our data also show that S1P receptor expression is deregulated in primary OSCCs and that S1PR2 is over-expressed in a subset of tumours, which in part mediates S1P-induced migration of OSCC cells." (PMID 27160553, 2016). "We showed that while there was weak/moderate staining in normal tonsillar epithelium (mean H-score of 68; range 5–120), S1PR2 was over-expressed (H-score >120; range 120–285) in 16 of 41 tumours (39%)." (PMID 27160553, 2016). "We also demonstrate that S1P receptor expression is deregulated in primary OSCCs and that S1PR2 is over-expressed in a subset of tumours, which in part mediates S1P-induced migration of OSCC cells." (PMID 27160553, 2016). "We demonstrate that S1P contributes to a more motile and invasive phenotype in OSCC cells and that there is a general deregulation of the S1PRs in OSCC, with a subset of tumours over-expressing S1PR2 at both the mRNA and protein level." (PMID 27160553, 2016). "In hepatocytes, S1PRs, especially S1pr1 and S1pr2, were only up-regulated in the pre-tumor group." (PMID 40057751, 2025). "Based on these mechanisms, targeting the SphK1/S1P/S1PR2 axis could not only suppress tumor proliferation and angiogenesis but also reverse EMT phenotypes and resistance, providing promising intervention strategies for precise HCC treatment." (PMID 41234914, 2025). "Moreover, S1PR2 functions in tumours through different pathways, including the JAK/STAT pathway, NF-KB pathway, ERK signalling pathway, and PI3K/AKT pathway." (PMID 36631680, 2023). "Additionally, the levels of mRNA and protein of S1PR2 were substantially lower in the tumours of mice in the sh-S1PR2 group." (PMID 36631680, 2023). "Moreover, S1PR2 was recently shown to act as a tumor suppressor in ABC-DLBCL and S1PR2 expression was prognostic in that setting." (PMID 38124747, 2023). "Moreover, the analysis of the LGG cohort demonstrated a similar profile to S1PR1, S1PR2, S1PR3, and S1PR4, which are upregulated in tumor tissue, significantly so for S1PR2 and S1PR3." (PMID 37760448, 2023). "In summary, S1PR2 promoted the in vivo growth of HCC tumours." (PMID 36631680, 2023). "Moreover, S1PR2 expressed in host endothelial cells and tumor-infiltrating myeloid cells in concert mediates the inhibition of tumor angiogenesis through the inhibition of vascular endothelial growth factor expression and matrix metalloproteinase 9 activity." (PMID 35216332, 2022). "However, in DLBCL, the forkhead box protein 1 directly inhibits S1PR2 and promotes tumor cell survival." (PMID 35237598, 2022). "Similarly, S1PR2 also showed anti-tumor effects on B-cell lymphoma and melanoma by inhibiting tumor growth, invasion, and migration." (PMID 34831211, 2021). "However, in a study on human neuroblastoma, JTE‐013‐mediated inhibition of S1PR2 actually blocked angiogenesis and tumor growth." (PMID 34289244, 2021). "To validate this hypothesis in an in vivo tumor model, we quantified pAKT in S1PR2+/+ and S1PR1−/− tumor-bearing mice." (PMID 33225975, 2020).
tumor (continued). "To address S1PR2 involvement in CRC, we first quantified protein levels, which confirmed the drastic reduction of S1PR2 expression in the tumor (TN0) compared to matched normal mucosa (p < 0.01), and second we characterized the tissue distribution of the receptor." (PMID 33225975, 2020). "S1PR2 is a critical receptor for the development and progression of different types of cancers and, although its role is controversial depending on the tissue, most data support an anti-tumor function." (PMID 33225975, 2020). "It is likely that in the initiation process of CRC, normal epithelial cells acquire oncogenic mutations through the interaction between internal and external factors that lead to the downregulation of S1PR2, which in turn triggers an excessive epithelial self-renewal and tumor development." (PMID 33225975, 2020). "The comparison analysis of S1PR2 between the epithelial compartment and the whole tissue confirmed that the receptor is constitutively present on the healthy epithelium and strongly down-regulated on tumor cells." (PMID 33225975, 2020). "In addition, S1PR2 can also inhibit tumor angiogenesis in mouse models, due to its dual nature in the pathogenesis of cancer." (PMID 31807117, 2019). "Interestingly, in contrast to S1PR1, S1PR2 was reported to limit tumor development and angiogenesis in one study, which involved S1PR2 on myeloid cells." (PMID 31379883, 2019). "S1PR2 is also involved in negative regulation of tumor angiogenesis and tumor growth in vivo via RhoC activation, although one study has shown that the growth of SKOV3 cells could be decreased by S1PR2 inhibition in vitro and in vivo." (PMID 29987226, 2018). "We opted to validate the expression of S1PR2 by immunohistochemistry because this receptor is thought to be more involved in cancer pathogenesis and we confirmed that the S1PR2 was protein was elevated in 39% of tumours." (PMID 27160553, 2016). "Only S1PR2 was expressed more strongly in tumor tissue than in normal liver tissue (p < 0.05)." (PMID 26090720, 2015). "S1PR2 expression is also higher in human CCA tissues compared to non-tumor samples." (PMID 26090720, 2015). "For example, S1PR2 signaling has been shown to inhibit tumor angiogenesis and cell migration, thereby restricting tumor growth, with S1pr2−/− mice exhibiting a two-fold increase in tumor microvessels compared to WT controls, supporting a protective role for S1PR2 in limiting tumor vascularization." (PMID 41511294, 2025). "Furthermore, the role of S1PR2 in tumor is still controversial." (PMID 36631680, 2023). "Furthermore, pharmacological inhibition of S1PR2, which may increase the attraction of immune cells to the tumor site, may by itself serve as an amplifier for tumor development." (PMID 35163211, 2022). "Thus, S1PR1 and S1PR2 may show opposing effects on tumor angiogenesis, making S1PR1 a potentially more interesting target when focusing on TAM." (PMID 31379883, 2019). "In HCC, S1P activates the Hippo pathway downstream effector YAP via S1PR2, inducing the expression of cysteine-rich protein 61 (CYR61) and connective tissue growth factor (CTGF), thereby driving abnormal tumor cell proliferation." (PMID 41234914, 2025). "Treatment with the S1PR2 inhibitor JTE-013 markedly inhibited the progression of the pro-fibrotic phenotype in HPCs, which consequently reduced tumor growth and fibrosis in rats." (PMID 41408647, 2025). "Its mediation of the S1P/S1PR2 axis further facilitates epithelial-mesenchymal transition (EMT) and chemotherapy resistance, and it can also exacerbate immune suppression in the tumor microenvironment by regulating the NF-κB inflammatory pathway." (PMID 41234914, 2025). "S1PR2 inhibitors (e.g., JTE-013) suppress tumor invasiveness in CCA preclinical models by inhibiting ERK/AKT/NF-κB signalling cascades." (PMID 41018102, 2025).
tumor (continued). "Yet, another tumor suppressor, miR-126, suppresses T and B-cell migration—a key lymphomagenesis event—by targeting the G protein-coupled receptor (GPCR), S1PR2." (PMID 36672402, 2023). "Additionally, S1PR2 expression is seen in host endothelial cells and tumor-infiltrating bone marrow cells, where it suppresses the expression of vascular endothelial growth factor and matrix metalloproteinase-9 activity to prevent tumor angiogenesis and tumor growth." (PMID 37265797, 2023). "Key pathways activated in neoplasias by BAs are regulated by nuclear receptors, FXR, CAR, SHP, PXR, LXR and VDR and other membrane receptors such as S1PR2, TGR5, CHRM2 and CHRM3." (PMID 35429253, 2022). "Similar to S1PR2 so far most studies addressing the function of S1PR3 in cancer concentrated on its role in tumor cells." (PMID 35163211, 2022). "The first study showed a varied expression profile of all three receptors without any trend along CRC tissues analyzed, whereas a second one an increased expression of S1PR2 and S1PR3 in tumor samples compared to normal tissue samples." (PMID 33225975, 2020). "The immunoexpression of anti-caspase 3 showed lower apoptotic cells in the tumor region compared to healthy surrounding regions of both S1PR2+/+ and S1PR2−/− mice, indicating an enhanced survival of cancer cells." (PMID 33225975, 2020). "In this study, we identified SPHK1, S1P, S1PR2, and p38 MAPK as essential for the TGF-β-mediated induction of myofibroblastic differentiation and the acquisition of a tumor-promoting CAF phenotype." (PMID 26716409, 2016). "S1PR2 activation by conjugated BAs upregulates COX-2/PGE2 signalling, which directly suppresses CD8+ cytotoxic T lymphocyte activity while promoting regulatory T cell infiltration, thereby establishing an immune-evasion niche conducive to tumor progression." (PMID 41018102, 2025). "In addition, we investigated the S1PR2 impacts on the biological behaviour of HCC cells and tumour formation in animal models." (PMID 36631680, 2023). "Additionally, recent data have suggested that targeting S1PRs in a more specific manner, such as S1PR2 and S1PR4 blockade, displayed an anti-tumoral effect or limited chemotherapy resistance in other tumor indications." (PMID 37760448, 2023). "Further, AID−/−/Eμ-TCL1 CLL cells downregulate the tumor suppressive SMAD1/S1PR2 pathway and have altered homing to non-lymphoid organs." (PMID 36042317, 2022). "Nevertheless, naïve S1PR2−/− mice showed normal architecture of the gut without developing tumor formations within their lifetime." (PMID 33225975, 2020). "This idea is further supported by recent work in the Ogretmen laboratory where it was demonstrated that systemic sphingosine kinase 1-generated S1P regulates metastatic potential, but not tumor S1P, via regulation of tumor S1PR2/Brms1 signaling." (PMID 24970174, 2013). "The inhibition of S1PR1 and S1PR3, but not S1PR2, could attenuate tumor angiogenesis and inhibit the expression of angiogenic factors." (PMID 35201458, 2021). "Then, to test whether S1PR2 acts as a brake of tumor proliferation, we used lentivirus-mediated overexpression of S1PR2 in RKO (RKO-S1PR2-OE), which exhibited, at least in our hands, the highest infection efficiency among all cell lines negative for S1PR2." (PMID 33225975, 2020).
cancer (44 papers, 2011 to 2026). A tumor composed of atypical neoplastic, often pleomorphic cells that invade other tissues. "The expression of sphingosine 1-phosphate receptor 2, which is associated with the order Lactobacillales and cancer progression in mouse models, was inversely associated with aggressive phenotype and weight gain in patients with PCa using the NCBI Gene Expression Omnibus database." (PMID 35216332, 2022). "In line with our previous data, S1PR2 expression was deficient in all cancer cells." (PMID 33225975, 2020). "Furthermore, S1PR2 was reported to be associated with various cancers." (PMID 35372340, 2022). "More detailed experimental work is needed to identify the exact role of S1PR2 in the regulation of cell proliferation and cancer progression." (PMID 39854311, 2025). "These microbiota-shaped BAs, by engaging a repertoire of host receptors—including FXR, TGR5, VDR, and S1PR2—on immune, stromal, and cancer cells, collectively orchestrate a complex signaling network." (PMID 40821794, 2025). "S1P produced by SK1 regulates the phosphorylation of FAK through binding to the G-protein coupled receptor S1PR2, which regulates the expression of genes that control invasion, angiogenesis, and migration in cancer cells." (PMID 36500220, 2022). "S1PR2 has opposing roles in cancer cells which seems to depend on specific molecular and cellular context given that S1PR2 can couple to multiple Gα proteins, such as Gi, G12/13 and Gq, and can thus induce different signaling events." (PMID 32456134, 2020). "In parallel, histologic examination highlighted a significantly higher number of carcinomas in S1PR2−/−Apcmin/+ (2.40 ± 0.51) compared to S1PR2+/+Apcmin/+ mice p = 0.041." (PMID 33225975, 2020). "For the most part, binding of S1PR1 has been shown to promote migration of several cancer cell lines, while S1PR2 exerted opposite effect." (PMID 27800303, 2016). "A very recent report showed that activation of S1PR2 in epithelial cells was crucial for elimination of neighboring cancer cells, a process known as epithelial defense against cancer (EDAC)." (PMID 27800303, 2016). "S1PR1 and S1PR3 are shown to be involved in migration and invasion of cancer cells, whereas S1PR2 plays inhibitory roles in migration and invasion of cancer cell lines and trophoblast cells." (PMID 25188412, 2014). "Targeting S1PR2 might therefore be a potential therapeutic strategy, however, the S1PR2-mediated signaling pathway in the regulation of cell proliferation and cancer progression remains controversial." (PMID 39854311, 2025). "Since S1PR2 signaling counteracts the pro-migratory functions of S1PR1 in leukocytes, one might argue that antagonizing S1PR2 could serve as potential target in cancer therapy by strengthening the chances to turn immunologically cold tumors into hot tumors." (PMID 35163211, 2022). "Additionally, a genetic loss of SphK1 led to an activation of a metastasis suppressor known as Breast Carcinoma Metastasis Suppressor 1 (Brms1) via S1PR2 in cancer cells." (PMID 34690821, 2021). "Information on whether S1PR2 participates in colorectal carcinogenesis/cancer is scanty, and we set out to fill the gap." (PMID 33225975, 2020). "S1PR2 has been shown to inhibit cell migration in cancer cell lines." (PMID 33225975, 2020). "In addition, some studies have found that S1PR2 plays a dual role in the progression of cancer by modulating a diverse range of downstream second messengers." (PMID 31807117, 2019). "Surprisingly, S1PR2 also plays an important role in suppressing cancer." (PMID 31807117, 2019). "Most of the existing studies only indicate the role of S1PR2 in certain tumors, and the next breakthrough involving S1PR2 will probably rely on actively exploring this dual-effect mechanism in order to reduce or remove the cancer-promoting effect and/or improve the anti-cancer effect." (PMID 31807117, 2019).